SOX5 (SRY-box transcription factor 5)
Diseases named in the same sentence as SOX5 in open-access papers (continued):
Sharing a sentence is not in itself a finding about the gene and the disease.
osteosarcoma (7 papers, 2014 to 2024). A usually aggressive malignant bone-forming mesenchymal neoplasm, predominantly affecting adolescents and young adults. "For example, in osteosarcoma, SOX5 overexpression promotes EMT by regulating Snail, and can increase the level of EMT markers in gastric and lung cancer to enhance cell migration and invasion." (PMID 38835366, 2024). "SOX5 has been shown to be highly expressed in osteosarcoma and act as a tumor promoter." (PMID 38835366, 2024). "Interestingly, studies in osteosarcoma have shown that ILF3-AS1 can competitively bind miR-212 to promote the SOX5 axis, and thus enhancing the proliferation, migration and invasion of osteosarcoma cells." (PMID 33996578, 2021). "Abnormally expressed SOX5 promotes EMT by up-regulating Snail, and thus significantly promotes osteosarcoma cell migration (p < 0.05) and invasion (p < 0.05)." (PMID 38835366, 2024). "In osteosarcoma, ILF3-AS1 was induced by SP1 and promoted the proliferation, migration and invasion of osteosarcoma cells through miR-212/SOX5 axis." (PMID 32117452, 2020).
lung carcinoma (6 papers, 2018 to 2026). "Comparison of SOX5 expression with the in vitro invasive capacity of lung carcinoma cell lines and bronchial epithelium cell line (16HBE) revealed that SOX5 mRNA and protein levels are positively correlated with cell invasive capacity." (PMID 29541384, 2018). "An in vivo zebrafish xenograft cancer model also showed SOX5 knockdown was followed by reduced lung cancer cell proliferation and metastasis." (PMID 29541384, 2018). "Many studies have investigated the role of SOX5 in lung cancer." (PMID 31729835, 2020). "SOX5 is significantly upregulated in primary lung cancer tissues and acts as a tumor metastasis promoting gene in lung cancer, and its overexpression promotes cell invasion and metastasis, while inhibiting SOX5 can inhibit tumor metastasis promoting genes in lung cancer." (PMID 38835366, 2024). "However, knocking out SOX5 can inhibit the proliferation and metastasis of lung cancer cells." (PMID 38835366, 2024). "For example, ciRS‐7 promotes lung cancer progression through the miR‐7/RELA signaling pathway, while other studies have shown that ciRS‐7 also drives carcinogenesis via the miR‐219a/SOX5 axis in the same cancer type." (PMID 41541658, 2026). "In contrast with the research in SOX5, studies on the role of SOX6 in lung cancer are relatively rare." (PMID 31729835, 2020).
Arthritis (5 papers, 2016 to 2024). Inflammation of a joint. "Collectively, these results indicate that local suppression Sox5 expression ameliorates arthritis and bone loss in CIA mice likely by inhibiting Rankl expression." (PMID 27550416, 2016). "Our previous data showed that local knockdown of SOX5 expression decreased arthritis incidence almost by 50%, and markedly inhibited synovitis, synovial hyperplasia, and bone erosion in a murine CIA model." (PMID 29706965, 2018). "Functional enrichment further supported that the primed genes are heavily involved in inflammatory response, arthritis-promoting functions (Ccl2, Cxcl5, Sphk1) and, interestingly, Wnt pathway (Bmp2, Rspo3, Cd44) and stem cell differentiation (Sox5, Nrp2, Cdk6)." (PMID 35879783, 2022).
chondrodysplasia (5 papers, 2014 to 2025). "In a relevant study, SOX5 single-null mice were born with mild skeletal abnormalities, and SOX5 double-null embryos died on day 16.5 of gestation due to severe, generalized chondrodysplasia." (PMID 40274769, 2025). "Although single null mice of Sox5 or Sox6 showed mild chondrodysplasia, double-null mice of Sox5 and Sox6 exhibit severe chondrodysplasia." (PMID 25546433, 2014). "Inactivation of SOX5 leads to minor defects in cartilage and skeletogenesis in mice, whereas SOX5/SOX6 double knockouts have severe chondrodysplasia." (PMID 30261039, 2018). "Although double knockout of Sox5 and Sox6 leads to severe chondrodysplasia, lacking either of them has modest skeletal defects, suggestive of genetic redundancy." (PMID 36289842, 2022).
epilepsy (5 papers, 2021 to 2026). A brain disorder characterized by episodes of abnormally increased neuronal discharge resulting in transient episodes of sensory or motor neurological dysfunction, or psychic dysfunction. "Among the other 21 de novo variants in curated epilepsy or seizure-associated genes, two deep intronic variants on SOX5 (IS05) and WWOX (IS06) had high CADD scores above 15 (17.92 and 17.91, respectively)." (PMID 35937050, 2022). "He found that a large number of top genes for epileptogenesis are regulated by key transcription factors, such as MEF2 (myocyte enhancer factor 2) and SOX5, which are interesting candidates for the pathogenesis of epilepsies." (PMID 39075495, 2024). "According to these studys, we speculate that SOX5, as a transcription factor gene, may be involved in the regulation of the expression of known epilepsy genes, and this interesting gene deserves further investigation." (PMID 39075495, 2024). "Additionally, the involvement of the SOX5 gene in epilepsy pathogenesis was not addressed." (PMID 39075495, 2024).
rheumatoid arthritis (5 papers, 2020 to 2025). A chronic, systemic autoimmune disorder characterized by inflammation in the synovial membranes and articular surfaces. "In fibroblast-like synoviocytes from rheumatoid arthritis patients, silencing SOX5 decreased IL-6 expression and reduced MMP-1,-2, and -9." (PMID 36835058, 2023). "The TF Sox5 was related with inflammatory response in rheumatoid arthritis fibroblast-like synoviocytes." (PMID 33717169, 2021). "Moreover, miR-212-3p decreased SOX5 expression to retard proliferation and strengthen apoptosis of fibroblast-like synoviocytes in rheumatoid arthritis." (PMID 34783627, 2021).
colorectal cancer (4 papers, 2019 to 2022). A primary or metastatic malignant neoplasm that affects the colon or rectum. "Moreover, lnc-sox5 was significantly upregulated in colorectal cancer tissues and lnc-sox5 knockdown promoted the cytotoxicity and infiltration of CD8+T cells." (PMID 31448238, 2019). "Lnc-sox5 regulates the CD8+T cells infiltration and cytotoxicity through modulating the expression of IDO, further affecting the progression of colorectal cancer." (PMID 31448238, 2019). "Mechanistic evidence revealed that lnc-sox5 regulated the CD8+T cell infiltration and cytotoxicity through modulating the expression of IDO and therefore affecting the progression of colorectal cancer." (PMID 31448238, 2019).
lumbar disc degeneration (4 papers, 2018 to 2025). "Among CBP-related traits examined, the lead SNP in SOX5, rs12310519, was most strongly associated with imaging-detected lumbar intervertebral disc degeneration (p = 1.1×10−4)." (PMID 30261039, 2018). "SRY-box transcription factor 5 (Sox5), a novel signaling factor, correlates with conditions such as back pain and lumbar intervertebral disc degeneration." (PMID 39889821, 2025). "For instance, the genes found in chronic back pain are involved in chondrogenesis (SOX5 and SOX673) or lumbar disc degeneration (CCDC26/GSDMC8)." (PMID 37144689, 2023).
nasopharyngeal carcinoma (4 papers, 2010 to 2024). A carcinoma arising from the nasopharyngeal epithelium. "One report suggests that over expression of SOX5 enhances nasopharyngeal carcinoma progression and correlates with poor survival." (PMID 22355333, 2012). "In nasopharyngeal carcinoma, SOX5 is significantly up-regulated in cancer cells, and the high expression of SOX5 promotes the proliferation and migration ability of nasopharyngeal carcinoma cells, and is negatively correlated with the survival rate of patients with nasopharyngeal carcinoma." (PMID 38835366, 2024). "Decreased expression of SPARC, an important mediator of cell-matrix interaction, was previously observed in Nasopharyngeal carcinoma (NPC) and in the same system SOX-5 turned out to be upregulated." (PMID 20731828, 2010).
osteoporosis (4 papers, 2015 to 2023). A condition of reduced bone mass, with decreased cortical thickness and a decrease in the number and size of the trabeculae of cancellous bone (but normal chemical composition), resulting in increased fracture incidence. "SOX5 was found to be up regulated in human MSCs isolated from bone marrow samples of postmenopausal osteoporosis patients, and it was recognized as a therapeutic target through regulation of the KLF4 signalling pathway in the treatment of this osteoporosis in females." (PMID 36614288, 2023). "Elevated expression of SOX5 has been evident in bone marrow-derived MSCs of postmenopausal osteoporosis patients and its overexpression inhibits the osteogenic differentiation of MSCs supported by reductions in ALP activity and osteoblast marker levels (Collagen I and Runx2)." (PMID 35468879, 2022). "Given that extensive inhibit of RANKL expression could affect bone turnover, our study positions selective blockage of SOX5 as a potential novel therapeutic target for RA and possibly other bone resorptive diseases, such as osteoporosis." (PMID 27550416, 2016). "We highlighted signatures of possible selection at 12 genes/regions relevant to appearance (e.g., SOX5 along BCDO2) and production traits, exemplified by a striking evidence of selection at OPG, a gene involved in Osteoporosis a disorder related to overconsumption of calcium in egg-laying hens." (PMID 26568375, 2015).
prostate carcinoma (4 papers, 2016 to 2024). A carcinoma that arises from epithelial cells of the prostate gland. "For example, in prostate cancer, SOX5 has been shown to be significantly upregulated in prostate cancer tissue, and overexpression of SOX5 is associated with larger tumor size, later clinical stage, and poorer prognosis." (PMID 38835366, 2024). "Moreover, in prostate cancer, evidence from the TCGA database suggests that SOX5 is associated with prostate progression." (PMID 38835366, 2024). "The increase of miR-139–5p greatly inhibits the expression of SOX5 in prostate cancer cells, down-regulates TWIST, and reduces the expression of N-cadherin and vimentin, thereby inhibiting the EMT process and thus inhibiting the cell proliferation and cell migration of prostate cancer cells." (PMID 38835366, 2024). "SOX5 seems to enhance epithelial mesenchymal transition (EMT), leading to metastasis in breast and prostate cancers." (PMID 36673024, 2023).
chondrosarcoma (3 papers, 2010 to 2017). A malignant cartilaginous matrix-producing mesenchymal neoplasm arising from the bone and soft tissue. "Together, these three transcription factors are thought of as the chondrogenic master regulators and Sox9 binding sites were previously found at the Sox5 locus in a ChIP-on-chip experiment using rat chondrosarcoma cells." (PMID 28630873, 2017). "Besides this, Liu and Lefebvre found that the regulatory trio of SOX9, SOX5 and SOX6 cooperatively work together to activate super-enhancers in a genome-wide way in rat chondrosarcoma cells." (PMID 26927636, 2016). "As chromatin source for ChIP-on-chip experiments, we used rat chondrosarcoma cells (RCS cells), because these cells display many chondrogenic characteristics including secretion of specific cartilage ECM proteins and high contents of SOX9, SOX5 and SOX6." (PMID 20404928, 2010).
language disorder (3 papers, 2021 to 2024). A category of disorders characterized by an impairment in the development of an individual's language capabilities, which is in contrast to his/her non-verbal intellect. "Similarly, it was also reported that patients with mental retardation or growth impairment with significant language disorder, behavioral issues, and mild dysmorphic traits have been shown to have Sox5 mutations." (PMID 37508024, 2023).
male infertility (3 papers, 2017 to 2024). The inability of the male to effect fertilization of an ovum after a specified period of unprotected intercourse. "Genome Wide Association Study studies suggest that the SOX5 locus is associated with male infertility, and the high expression level of S-SOX5 in the testis implies that it plays an important role in regulating expression of the genes that are essential for sperm function and male fertility." (PMID 39075495, 2024). "Recent GWAS studies suggest that the SOX5 locus is associated with male infertility, and the high expression level of S-SOX5 in the testis implies that S-SOX5 plays an important role in regulating expression of the genes that are essential for sperm function and male fertility." (PMID 28137312, 2017). "In total, we found nine genes that were recorded to be associated with “male infertility” or “non-obstructive azoospermia,” and three of them (CLASP2, CRACR2A, SOX5) were identified in this study as zebrafish testis cell-type specific marker genes." (PMID 35360857, 2022).
Obesity (3 papers, 2008 to 2025). Accumulation of substantial excess body fat. "From the known functions of these genes, GNAL, HELIOS, and SOX5 are directly related to adipose tissue metabolism or obesity, while SLC9A3, SPOCK3, ANXA10, MYLK, and VSNL1 may be indirectly related." (PMID 24962627, 2014). "The lowest SOX5 and SOX9 mRNA expression levels in OA-affected synovium were noted in overweight patients, and the highest in patients with class II + III obesity." (PMID 40004707, 2025). "Relative to the BMI, SOX5 mRNA expression level was lowest in samples from overweight patients and highest in those with class II + III obesity." (PMID 40004707, 2025). "Our study revealed only SOX5 mRNA expression level in OA-affected articular cartilage with subchondral bone was positively correlated with BMI; however, we noticed SOX9 and SOX11 mRNA expression level was higher in patients with class II + III obesity compared to patients with class I obesity." (PMID 40004707, 2025).
ovarian carcinoma (3 papers, 2019 to 2025). A malignant neoplasm originating from the surface ovarian epithelium. "Furthermore, the clinical relevance of SOX5 as a therapeutic target was supported by a significant association between SOX5 overexpression and poor prognosis in ovarian cancer on public mRNA microarray data sets." (PMID 40274769, 2025). "Ectopic SOX5 overexpression contributed to PARP inhibitor resistance by suppressing DNA double-strand breaks (DSBs) in BRCA-mutated breast and ovarian cancer." (PMID 40274769, 2025). "The SOX5-High group exhibited shorter OS than the SOX5-Low group in five of seven data sets of ovarian cancer patients, although GSE18520 and GSE9891 analyses did not support our data (data not shown)." (PMID 40274769, 2025). "Independent public mRNA expression data sets were used to evaluate the impact of SOX5 overexpression on ovarian cancer prognosis." (PMID 40274769, 2025). "As a tyrosine kinase inhibitor, apatinib inhibits glycolysis by suppressing the VEGFR2/AKT1/SOX5/GLUT4 signaling pathway in ovarian cancer cells." (PMID 35069931, 2022). "SOX5 was exogenously over-expressed and silenced in ovarian cancer cells using expression vector and shRNA-based methods, respectively." (PMID 31325096, 2019). "Therefore, we propose SOX5 as a promising therapeutic target for overcoming PARP inhibitor resistance in BRCA1/2-mutated breast and ovarian cancer." (PMID 40274769, 2025). "The expression of VEGFR2/AKT1/SOX5/GLUT4 pathway proteins was assessed using Western blotting, and glucose uptake and lactate production assays were used to detect glycolysis in ovarian cancer cells." (PMID 31325096, 2019).
pituitary tumor (3 papers, 2020). A benign or malignant neoplasm affecting the pituitary gland. "SOX5, up-regulated in our study, was also upregulated in invasive pituitary tumor tissues and considered as an oncogene." (PMID 32192168, 2020).
schizophrenia (3 papers, 2023 to 2024). A major psychotic disorder characterized by abnormalities in the perception or expression of reality. "Regulation of DNMT3A depends on miR-29 expression pattern in postnatal brain during lifespan so that downregulation of miR-29 associated with increased CH methylation in genes such as CHL1, FZD3, and SOX5 which are associated with schizophrenia." (PMID 38705955, 2024).
Strabismus (3 papers, 2021 to 2025). A misalignment of the eyes so that the visual axes deviate from bifoveal fixation. "This region included the SOX5 gene, and it was known to cause non-progressive optic atrophy and strabismus." (PMID 35052368, 2021).
autoimmune disease (2 papers, 2020 to 2023). A disorder resulting from loss of function or tissue destruction of an organ or multiple organs, arising from humoral or cellular immune responses of the individual to their own tissue constituents. "Depending on the pattern of regulatory transcriptional factors such as SOX5, AHR and NFkB, the polarization of autoimmune diseases progresses in host cell differentiation and maturation." (PMID 36986457, 2023).
Azoospermia (2 papers, 2022). Absence of any measurable level of sperm,whereby spermatozoa cannot be observed even after centrifugation of the semen pellet. "In addition, the polymorphism of SOX5, which can lead to spermatogenic impairment, is associated with the risk of non-obstructive azoospermia." (PMID 35883696, 2022).
COVID-19 (2 papers, 2021 to 2023). A disease caused by infection with severe acute respiratory syndrome coronavirus 2. "Although they were not enriched in autoreactive B cells, two distinct memory populations (CD80+/ISG15+ and CD11c+/SOX5+/T-bet+/−) with signs of autoreactivity were identified, which were considered to be the source of COVID-19 autoantibodies." (PMID 37243231, 2023).
liver disease (2 papers, 2022 to 2025). "This might indicate an ambivalent role in liver disease when not related to HCC, and more research is needed to elucidate the role of SOX5 in metabolic liver disease." (PMID 40489530, 2025).
metastatic disease (2 papers, 2016 to 2018). "This might point towards a dual functional role of SOX5 depending on primary versus metastatic tumor stage." (PMID 26927636, 2016).
metastatic melanoma (2 papers, 2008 to 2016). A melanoma that has spread from its primary site to another anatomic site. "We speculate that SOX5 could be an important factor during the transition from primary to metastatic melanoma, as SOX5 knockdown resulted in reduced invasion." (PMID 26927636, 2016). "We speculate that in metastatic melanoma the anti-proliferative effect of very low SOX5 and thus high MITF levels might lead to a diminished susceptibility to chemotherapy and thus to a worse prognosis." (PMID 26927636, 2016). "In contrast, the metastatic melanomas express higher levels of genes such as MAGE, GPR19, BCL2A1, MMP14, SOX5, BUB1, RGS20, and more." (PMID 18442402, 2008).
non-small cell lung carcinoma (2 papers, 2024 to 2025). A group of at least three distinct histological types of lung cancer, including non-small cell squamous cell carcinoma, adenocarcinoma, and large cell carcinoma. "By targeting SOX5 in non-small-cell lung cancer, miR-497-5p suppresses tumour cell proliferation and invasion." (PMID 38911367, 2024).
optic atrophies (2 papers, 2020 to 2022). "Optic atrophy was considered as a clinical feature of SOX5 gene deletion, known as Lamb–Shaffer syndrome." (PMID 36071901, 2022). "The variants in SOX5 (n = 1), SPG7 (n = 1), and SSBP1 (n = 1) genes were responsible for cases of other dominantly inherited optic atrophies." (PMID 36071901, 2022).
Abdominal obesity (1 paper, 2014). Excessive fat around the stomach and abdomen. "A recent study indicated SOX5 may play an important role in left ventricular mass regulation, a disease that may be affected by abdominal obesity." (PMID 24962627, 2014).